IL6 (interleukin 6)
Diseases named in the same sentence as IL6 in open-access papers (continued):
Sharing a sentence is not in itself a finding about the gene and the disease.
tumor (continued). "Among the factors identified, IL-6 emerged as a prominent factor secreted by tumor cells as well as cancer-associated fibroblasts derived from cancer patients." (PMID 37601096, 2023). "Tumor-derived granulocyte-colony stimulating factor (G-CSF), IL-6, VEGF, and CCL2 cause MDSCs migration to HCC-TME." (PMID 37007125, 2023). "Simultaneously, a study also showed that the tumor-promoting effect of myofibroblasts was associated with IL-6 and IL-8, the two major SASP factors." (PMID 37046588, 2023). "Along with the mutated genes for JAK in the occurrence of some tumors, IL-6 also contributes to JAK/STAT3 constitutive activation in tumor cells, thus enabling proliferation, survival, and suppression of antitumor immune response." (PMID 37176160, 2023). "STAT3 signaling and macrophage-produced IL-6 that promotes tumor cell proliferation are linked to TAM-mediated resistance to carboplatin." (PMID 37211559, 2023). "Fibrinogen can promote the production of interleukin 6, which is involved in the inflammatory response and causes tumor progression." (PMID 37051547, 2023). "IL-6 also functions to recruit an inflammatory immune population such as tumor-associated macrophages and contribute to a immunosuppressive microenvironment needed for evasion." (PMID 36980608, 2023). "More specifically, high Il-6 serum levels have been associated with poor OS, since IL-6 enhances tumorigenesis through paracrine and autocrine mechanisms and impairs the role of the anti-tumor immune response." (PMID 38068319, 2023). "Our results demonstrated that tumor-associated MCs harbor a main connective tissue phenotype and release high amounts of Interleukin (IL)-6 and Tumor Necrosis Factor (TNF)-α." (PMID 37730723, 2023). "Recent data has shown that IL-6 is an important cytokine associated with the development of irAEs Additionally, blocking both IL-6 and PD-1/PD-L1 provides synergistic anti-tumour effect." (PMID 38414933, 2023). "Though, tumor and tumor associated stromal cells secrete all these cytokines in a great extent, we found MDSCs are the major contributors in releasing IL-10, IL-6 and IL-1β over tumor cells itself." (PMID 38304256, 2023). "The best studied of them, IL-6 and IL-8 are produced by the tumor-associated macrophages (TAMs) and promote HCC development through different signaling pathways." (PMID 38138294, 2023). "Cancer-associated fibroblasts (CAFs) and tumor-associated macrophages (TAMs) significantly contribute to this process, secreting pro-inflammatory cytokines such as interleukin-6 (IL-6) and tumor necrosis factor-alpha (TNF-α)." (PMID 37760852, 2023). "This T cell exhaustion phenotype was corroborated by the significantly lower concentrations of various T-cell associated inflammatory cytokines, such as IFN-γ, TNF-α, IL-6 and IL-17A, in the plasma of tumor-bearing aging mice." (PMID 37752597, 2023). "Immunosuppressive factors, such as TGF-β, IL-6, IL-10, and IL-23 secreted by MDSCs, TAMs, and Tregs, suppress NK cell function, causing cancer-immune evasion and promoting tumor progression." (PMID 36769116, 2023). "Another study showed that suppression of IL6 derived from a subset of carcinoma-associated fibroblasts reduced PDAC tumor burden in gemcitabine-treated mice." (PMID 36672405, 2023). "In particular, IL-6 is a well-known pro-inflammatory cytokine associated with the tumor microenvironment and has been reported to promote cell cycle progression, proliferation, anti-apoptosis, and metastasis in breast cancer." (PMID 37069244, 2023). "On the other hand, tumors with a high epithelial IL-6 expression showed a significant tumor-infiltrating myeloid infiltration and were associated with a reduced survival time." (PMID 37298230, 2023). "The M2d sub-type, commonly referred to as tumor-associated macrophages (TAMs), promotes tumor progression by secreting TNFα, IL6, IL-10, TGFβ, and Vascular Endothelial Growth Factor A (VEGFA)." (PMID 37371552, 2023).
tumor (continued). "Remarkably, evidence from some prospective trials demonstrated the association between postoperative increases of IL-6 in serum and poor tumor response, as well as shorter PFS in LIT-treated HCC." (PMID 36831664, 2023). "Macrophage-associated cytokines IL-1 β, TNF- α and IL-6 increase more in tumor-associated colitis and promote the stemness of Dclk1+ tuft cells, which is the cellular origin of colon tumors." (PMID 38273841, 2023). "Among these cytokines, the function of interleukin-6 (IL-6) as a master regulator of tumor-associated inflammation and tumorigenesis is well established." (PMID 37292297, 2023). "IL-6 then orchestrates recruitment of tumor-associated macrophages of the M2 suppressive phenotype which produce anti-inflammatory cytokines like IL-10 and TGF-β, which in turn inhibit tumor-associated T-cell invasion and activation." (PMID 38188300, 2023). "Another line of immune cells, IL-17 producing CD4+ T-cells (Th17), are stimulated and expanded by the expression of TGF-β, IL-6 and IL-23 in the tumor micro-environment, and are believed to be implicated in tumorigenesis." (PMID 37681925, 2023). "In this study, interaction of M1 macrophages with C1GalT1-suppressed tumour cells is associated not only with higher tumour cell engulfing but also with lower macrophage secretion of IL-6 in comparison to their interaction with higher C1GalT1-expressing cells." (PMID 37612278, 2023). "In this context, interleukin-6 (IL-6) modulates the tumor microenvironment and high levels have been associated with advanced disease and higher risk of brain metastases." (PMID 38023992, 2023). "Immuno-suppressive effects can be IR-induced by high doses when there is low tumor immunogenicity and low tumor antigen production associated with the induction of immunosuppressive cytokines, such as IL-6 and TGFβ, in the TME." (PMID 37511215, 2023). "Our results show that high IL-6 is associated with higher levels of MDSCs which suppress anti-tumor immunity, such as CD8+ cells." (PMID 37733188, 2023). "Cell cycle-related kinase (CCRK) now known as CDK20 has been specifically implicated in tumor-mediated immunosuppression by induction of MDSC in response to IL-6 upregulation." (PMID 38188300, 2023). "The key pro-inflammatory factor IL-6 has been implicated to be involved in the tumor progression and MDR of various cancers." (PMID 36757936, 2023). "The monocytes in the TME differentiate under the influence of IL-6 and CSF-1 into macrophages, specifically tumor-associated macrophages (TAMs)." (PMID 37736898, 2023). "Interleukin-6 (IL-6) can also be produced by many tumor-associated stromal cells, including tumor-associated innate immune." (PMID 37370720, 2023). "Its activation on DCs is associated with decreased cAMP, IL-6, IL-12, and prevents tumor-specific antigen presentation." (PMID 36993986, 2023). "STAT3 is an oncogenic transcription factor with potent immunosuppressive functions, and activation of the IL-6/gp130/STAT3 pathway is associated with tumor progression and M2-polarized TAMs with pro-tumoral effects." (PMID 37553327, 2023). "IL6 is a proinflammatory cytokine and has been associated with tumour progression, proliferation, differentiation, and aggressivity." (PMID 37031328, 2023). "Tumor cells can cause N2 transformation in pre-metastatic niche by secreting IL-6, IL-10, G-CSF, and TGFβ to pre-metastatic niche or inducing cells in pre-metastatic niche to produce these factors." (PMID 37158964, 2023). "The secretion of IL6 is caused by tumor stimulation of adipocytes, as shown by co-cultivation of murine adipocytes with human BC cell line ZR75.1." (PMID 37445860, 2023). "Inflammatory cytokines, including interleukin-6 (IL-6), are mediators of tumor-associated inflammation that can lead to elevated CRP." (PMID 37936161, 2023).
tumor (continued). "Studies have shown that senescence tumor-associated fibroblasts (CAFs) can synthesize and secrete large amounts of IL-6 and other SASP factors, thus promoting the invasion and metastasis of pancreatic cancer." (PMID 36950520, 2023). "report that IL-6 deficient mice showed significantly decreased tumour growth of colon cancer compared to wildtype mice." (PMID 35479076, 2022). "OS extracellular vesicles can cause MSCs to shift to the pro-tumor phenotype distinguished by abundant IL-6 production." (PMID 35433427, 2022). "On the contrary, Th2 associated cytokines such as IL-4, IL-6 and IL-10 support tumor growth and suppress cellular immunity." (PMID 35565378, 2022). "In a 2020 article, it was reported that TNF-α can be used as a prognostic indicator, while various ILs (IL-2, IL-1β, and IL-6) were also discovered to be linked to tumor prognosis." (PMID 35677632, 2022). "CCA, as a tumor, in which the pathogenesis is highly related to an inflammatory process, is associated with elevated IL-6 levels." (PMID 35326644, 2022). "The association between PET-based hypoxia and IL-6 was examined using Pearson’s correlation and multiple regression analyses, and the diagnostic power of IL-6 for tumor hypoxia response prediction was determined with receiver-operating characteristic analyses." (PMID 34773163, 2022). "IL-6 is a key pleiotropic immunomodulatory cytokine secreted by both normal and tumour cells, and its role in inflammatory-associated carcinogenesis, tumour growth, and angiogenesis has been extensively described." (PMID 36007304, 2022). "Unlike other studies, in which IL-6 is knocked out in the entire animal, this approach narrows the IL-6 deficiency to the 4T1 tumor cells responsible for eliciting the MDSC and type 3 Th responses." (PMID 36142210, 2022). "The selective expression of IL-6 and IL-1 mRNA is intriguing as both are implicated in the induction of myeloid-derived suppressor cells in the tumour microenvironment." (PMID 36430641, 2022). "They secrete various cytokines (such as IL-23, IL-17, and IL-6), which cause tumor-induced inflammation and promote tumor growth." (PMID 35205204, 2022). "IL-6 that is secreted by stromal CAFs recruits tumor-associated macrophages and promotes their transition to an immunosuppressive phenotype (M2)." (PMID 36010993, 2022). "The four-period cycle attractor M1/M1M2c/M1/M1M2c is associated with the expression of a pleiotropic IL-6, which is implicated in acute inflammation and tumor proliferation." (PMID 36544764, 2022). "Interleukin-6 (IL-6) is a key proinflammatory cytokine associated with promoting invasion, tumour survival, chemoresistance, and angiogenesis via VEGF overexpression in OC cells." (PMID 35645374, 2022). "The plasma concentration of proinflammatory cytokines, such as IL-1β, TNF-α, and IL-6, increases in several types of cancer due to the sustained inflammatory environment caused by the tumor and its stroma." (PMID 36072935, 2022). "Tumor development in this murine model was closely associated with the release of different proinflammatory and protumorigenic cytokines such as TNFα and IL6." (PMID 35267563, 2022). "Other studies have shown that the blockade of IL6-associated inflammation positively correlates with the inhibition of tumor growth and EMT process, which should be further explored in TNBC." (PMID 35563174, 2022). "Tumour necrosis factor (TNF-α) and interleukin-6 (IL-6) are multifunctional cytokines implicated in tumour growth and metastasis." (PMID 35980113, 2022). "The paracrine cytokines secreted by cancer-associated fibroblasts, such as TGFβ, CXCL12, CCL2 and IL-6, have been identified as important signaling molecules for tumor progression and immunosuppression in the microenvironment." (PMID 35628489, 2022). "Overexpression of IL6 has been reported to be associated with tumor progression through inhibition of cancer cell apoptosis, stimulation of angiogenesis, and drug resistance." (PMID 35399006, 2022).
tumor (continued). "The signal transducer and activator of transcription 3 (Stat3) can be activated by IL-6 through phosphorylation and plays a crucial role in carcinogenesis through tumor-associated immunosuppression." (PMID 36454780, 2022). "High concentrations of IL-6 in the tumor microenvironment were identified as one of the main causes of cancer growth, and lactate plays an important role in the expression of IL-6 and the activation of the STAT3 signaling pathway." (PMID 36686771, 2022). "Several studies have reported that HCC patients with significantly high plasma IL-6 levels are at a high risk of postoperative tumor recurrence." (PMID 35432524, 2022). "CAFs-derived IL-6 participated in the activation of STAT3 signal in tumor‐associated neutrophils (TANs), which sustained the survival and function of TANs and inhibited T cell’s attack ability via the PD1/PD-L1 signaling." (PMID 36324128, 2022). "Elevated IL-6 was associated with activation of a browning program in WAT of cachectic mice while anti-IL-6 receptor antibody inhibited WAT browning in tumor-bearing mice." (PMID 35646636, 2022). "The factors (IGFBP5, CLCF1 and IL6) reported to be secreted by CAFs indeed showed significantly higher expression in the high-risk group, suggesting that fibroblasts in the tumor microenvironment of LUAD likely contribute to the poor outcome in LUAD patients." (PMID 35711936, 2022). "IL-6 signalling is associated with increased invasiveness, aggressiveness, and incidence of metastasis across many tumours." (PMID 36429126, 2022). "Platinum-induced secretion of IL-6 from cancer-associated fibroblasts in the tumor microenvironment promotes the enrichment of OCSC in residual tumors after chemotherapy through activation of STAT3 and up-regulation of ALDH1A1 expression." (PMID 36387165, 2022). "It has been shown that iNKT cells can indirectly control tumor growth through targeting tumor-supportive, IL-6-producing, CD1d+ CD68+ tumor-associated macrophages (TAM)." (PMID 35784290, 2022). "IL6-depletion resulted in the downregulation of PD-L2 expression on tumour-associated macrophages, endothelial cells, and DCs, suggesting that FAK-dependent expression of IL6 promotes PD-L2 expression in the PDAC TME." (PMID 36138073, 2022). "ARH-I can sequester STAT3, which mediates IL-6-transcriptional effects associated with tumor aggressiveness." (PMID 35565270, 2022). "Numerous interleukin-6 related signalling pathways have been linked and found with increased migration, invasion, and proliferation of several tumor cells." (PMID 36557997, 2022). "Tumour-indued IL6 is implicated in a systemic metabolic stress response and reprogramming of host metabolism, resulting in suppression of anti-tumour immunity in murine PDAC." (PMID 36358721, 2022). "Cancer-associated fibroblasts play important roles in tumor growth and maintenance through secreting autocrine and paracrine signaling molecules such as IL-1α, IL-1β, IL-6, IL-33, HGF, VEGF, TNF-α, TGF-β, CCL-2, CXCL-12, CXCR-4, MMP-2, and Snail." (PMID 35992863, 2022). "The expression of IL-6, IL-8, and IL-1β is strongly associated with tumor relapse, and protects the cancer cell from chemotherapy by enhancing multidrug resistance protein 1 and antiapoptotic protein expression." (PMID 35326493, 2022). "Tumor microenvironment-associated inflammation, mainly regulated by cytokines including IL-6, has been well-documented to contribute to every stage of cancer progression." (PMID 35924148, 2022). "Various cell types in the TME of cancers release IL-6, leading to the activation of the IL-6/JAK/STAT3 pathway in both tumour cells and tumour-associated immune cells, which in turn promotes tumour cell proliferation, invasiveness and metastasis." (PMID 36555253, 2022). "IL-18 is secreted from tumor-associated macrophages (TAMs) and stimulates tumor growth, similar to IL-6." (PMID 35892729, 2022).
tumor (continued). "Elevated levels of IL-6 are also associated with the formation of desmoplastic tumor stroma and can also stimulate the generation of MDSC cells in coordination with TGF-β." (PMID 35185894, 2022). "Serum IL-6 has previously been observed to be elevated in cancer patients compared to controls and has been linked to tumor burden and fatigue in cancer patients, both pre- and post-treatment." (PMID 36354718, 2022). "IL-6 has been shown to be involved in tumorigenesis, metastasis, and tumor-associated cachexia in various cancers and is considered one of the most relevant cytokines in cancer progression." (PMID 36361914, 2022). "For example, cytokines in the TME, such as TNF-α, IL-6, and IL-8, are associated with angiogenesis and tumor metastasis, whereas IL-4, IL-13, and IL-10 are associated with immune response suppression." (PMID 35844605, 2022). "Our secretomic data supports the role of IL-6/sIL-6Rα receptor trans-signaling as the key driver of tumor EMT and associated therapy resistance and increased metastatic potential." (PMID 35222439, 2022). "Paradoxically, IL-6 was also associated with pro-tumor Treg/Th17 cell response due to the observation that anti-IL-6 treatment promotes a T cell response switch, from a pro-tumor Treg/Th17 to an anti-tumor cytotoxic CD8+ T cell response." (PMID 35159208, 2022). "CD163+ tumor-associated macrophages can secrete IL-6 to activate tumor cells JAK2/STAT3, promoting EMT and CTC-mediated metastasis, which is closely related to poor prognosis of patients." (PMID 36568117, 2022). "The 3 main model drivers were plasma G-CSF, CXCL13 and IL-6 levels, with higher plasma amounts of these factors generally associating with larger 4T1 tumours." (PMID 35226704, 2022). "Tumor-associated astrocytes secrete IL-6 that activates JAK/STAT signaling, which is linked to the more aggressive progression of GBM." (PMID 35205842, 2022). "One study showed that tumor-associated macrophage-derived IL-6 activates the Janus kinase (JAK) 2/signal transducer and activator of transcription (STAT) 3 axis to modulate cell migration and invasion in CRC." (PMID 35463300, 2022). "Genetic ablation of IL-6 ameliorates tumor development in an AOM/DSS-elicited colitis-associated cancer model." (PMID 35954156, 2022). "Recent studies have also shown that hypoxia leads to an upregulation of IL-6, providing a rationale to investigate the association between plasma IL-6 concentration and tumor hypoxia dynamics as quantified by [18F]FMISO PET." (PMID 34773163, 2022). "The protein plays an important role in the development of cachexia, and high levels of circulating IL-6 are associated with increased tumour burden and short OS in patients with advanced PDAC." (PMID 35805022, 2022). "Despite differences in their signaling processes, IL-6 and IL-8 have recently been implicated in modulating the tumor microenvironment by regulating the function and activity of tumor-associated immune cells." (PMID 34689178, 2022). "Tumor-associated macrophages (TAMs) secreted IL-6 and plays critical role in carcinogenesis and differentiation of myeloid-derived suppressor cells (MDSCs), which gives rise to intra-tumoral inflammatory processes." (PMID 35924148, 2022). "In various cancers, the elevated systemic and tumor-associated levels of IL-6 and IL-8 are associated with reduced clinical benefit of anti-PD-1/PD-L1 treatment." (PMID 35359980, 2022). "High levels of IL-6 in the tumor microenvironment, possibly reflecting the strong association between inflammation and cancer, have been found in almost all tumor types." (PMID 36015338, 2022). "In many cancers, excessive activation of IL-6/JAK/STAT3 is associated with tumor cell proliferation, migration, invasion and inhibition of antitumor immune responses, and is associated with poor tumor prognosis." (PMID 35359408, 2022).